BUB1B (BUB1 mitotic checkpoint serine/threonine kinase B)
Diseases named in the same sentence as BUB1B in open-access papers (continued):
Sharing a sentence is not in itself a finding about the gene and the disease.
cancer (continued). "The Cancer Genome Atlas (TCGA) database data showed that the expression of BUB1B in CCA tissues was upregulated." (PMID 33431813, 2021). "AURKA and AURKB also consistently scored high across every cancer cohort, as did other cell-cycle- and mitoses-related kinases (BUB1B, BUB1, CDK1)." (PMID 33205077, 2020). "Among the top genes found by the PMN, ASXL2, BUB1B, KIF11 and TPX2 have been clinically proven to be associated with multi-cancers, which are a variety of genes commonly identified as mutated in cancers." (PMID 31888692, 2019). "On screening the top 200 linear model genes against cancer driver genes in the Cancer Gene Census, only four genes were found, namely BUB1B, CDKN2A, EZH2, and RECQL4." (PMID 31277598, 2019). "For example, we observe that PLK1, CCNB1/2, CCNA2, AURKB and BUB1B are shared across 6–9 cancer types and physically interact with several deregulated neighbouring genes in our activated modules." (PMID 31396397, 2019). "A human study reported that the role of BUB1B was to facilitate accurate chromosome segregation and maintain chromosomal stability, to suppress cancer." (PMID 30100882, 2018). "To determine the role of the N-terminal and internal Cdc20-binding domains in the protective effect of BubR1 overexpression on aneuploidy and cancer, we generated three distinct Flag-tagged mutant Bub1b transgenic mouse strains." (PMID 27528194, 2016). "Here, we used Bub1b mutant transgenic mice to explore the role of the amino-terminal (BubR1N) and internal (BubR1I) Cdc20-binding domains of BubR1 in preventing aneuploidy and safeguarding against cancer." (PMID 27528194, 2016). "In contrast, in human cancer tissues, overexpressed BUB1B protein is predominantly localized in the cytoplasm." (PMID 26000094, 2015). "It has been reported that spindle orientation in cultured mammalian cells is influenced by the ECM, and that BUB1B overexpression is significantly correlated with a higher rate of cell proliferation in some human cancers." (PMID 26000094, 2015). "Consistent with this, Bub1b+/−mice have been shown to be more cancer-prone compared to wild-type mice." (PMID 26000094, 2015). "Aberrant expression of spindle proteins such as the Aurora kinases and the spindle checkpoint proteins MAD2 and BUB1B, are thought to contribute to the development of chromosomal instability and DNA aneuploidy in cancer." (PMID 20411023, 2010). "Although most studies have demonstrated the function of BUB1B in cancer without fully elucidating the underlying mechanisms, several functional mechanisms of BUB1B have still been reported." (PMID 41163302, 2025). "BUB1B expression was markedly related to the stage of 11 types of cancer, including LUAD." (PMID 40076684, 2025). "Increased BUB1B expression, achieved through m6A modification, can restore the malignant characteristics, self-renewal capabilities, and resistance to immune responses in cancer stem cells." (PMID 40236649, 2025). "Given the essential function of BUB1b in the regulation of chromosome segregation, abnormal expression levels of BUB1b may result in chromosomal instability and an increased incidence of cancer." (PMID 40076684, 2025). "Moreover, we conducted an in-depth analysis of the correlation between BUB1B and 14 cancer functional states utilizing single-cell sequencing data from CancerSEA." (PMID 40076684, 2025). "We found that BUB1B was significantly upregulated and was correlated with the clinical stage in several cancers, and the ROC curve analysis shows that BUB1B may function as a diagnostic biomarker." (PMID 40076684, 2025). "Furthermore, significant chromosomal damage and apoptosis were seen in human cancer cells when the BUB1B level was lowered or BUB1B kinase activity was inhibited." (PMID 39911278, 2025). "Furthermore, an analysis based on the TISIDB database reveals that BUB1B expression in various cancers exhibits significant correlations with immune regulators." (PMID 40076684, 2025).
cancer (continued). "Considering the critical role of BUB1b in regulating chromosome segregation, the abnormal expression of BUB1b could lead to chromosomal instability and increased cancer incidence." (PMID 39043653, 2024). "Dysregulated expression of BUB1 and BUB1B led to cancer cell proliferation." (PMID 38375472, 2024). "Some cancer types show a significant association with mutations in well‐known cancer predisposing genes, that is, ovarian cancer in BRCA1/2, whereas new associations were revealed, such as loss of function mutations in BUB1B in lung cancer and in SDHA in melanoma." (PMID 39118233, 2024). "In colon adenocarcinoma, the silencing of BUB1b facilitated oncogenesis and progression, while the opposite phenomenon was observed in hepatocellular carcinoma, pancreatic ductal adenocarcinoma, and other cancers." (PMID 39043653, 2024). "BUB1 and BUB1B mutations have been associated with an increased risk of colon cancer but have not been linked with other cancers." (PMID 39048649, 2024). "The expression of BUB1b in HBE was significantly lower than in cancer cell lines." (PMID 39043653, 2024). "The impact of BUB1b was also heterogeneous in different cancers." (PMID 39043653, 2024). "This suggests BUB1B may contribute to cancer malignancy and progression through multiple mechanisms." (PMID 37055476, 2023). "As a result, we hypothesize that increased BUB1B expression may promote cancer formation and potentially treatment resistance by boosting tumor stemness and assisting in immune surveillance evasion." (PMID 37055476, 2023). "Genetic alteration types and frequency of BUB1B showed differences in pan-cancer." (PMID 37055476, 2023). "Given this, we investigated the genetic alteration of BUB1B in pan-cancer further." (PMID 37055476, 2023). "Thus, we further investigated the relationship between BUB1B expression and tumor immune environment in pan-cancer." (PMID 37055476, 2023). "The results showed that the alteration rate of BUB1B in pan-cancer was 2% of quired samples." (PMID 37055476, 2023). "Interestingly BUB1B was found to be significantly downregulated (logFC -2.60, adjusted p = 0.001) in the treated cell line with the highest connectivity score among cancer genes." (PMID 35847923, 2022). "Worse was that BUB1B was highly expressed in almost all cancers." (PMID 35517426, 2022). "BUB1B is positively correlated with FOXM1 in all the cancer types from TCGA." (PMID 35847923, 2022). "Budding uninhibited by benzimidazoles 1 (BUB1B), a mitotic checkpoint serine/threonine kinase, that serves an important role in chromosome alignment, has been shown to act as a tumor promoter in many cancers." (PMID 35847923, 2022). "In conclusion, we hypothesize that the upregulated HDAC2 in NPC induced cell cycle disorders by regulating BUB1B, and ultimately promotes the development of cancer." (PMID 36577966, 2022). "Even more, unfortunately, BUB1B was highly expressed in almost all cancers types including THCA." (PMID 35517426, 2022). "The expression of hsa-miR-130a-3p and BUB1B was assessed in cancer patients with different stages (I, II, III, and IV) to discover whether it is associated with clinicopathological features in multiple cancers." (PMID 36185088, 2022). "We continue to explore the protein level of BUB1B in pan-cancer using the HPA database." (PMID 36185088, 2022). "BUB1B is abnormally expressed in cancers of the liver, pancreas, lung, breast, and other organs." (PMID 36245843, 2022). "In summary, BUB1B was highly expressed in NPC, and HDAC2 may affect cell cycle by regulating BUB1B to promote cancer progression." (PMID 36577966, 2022). "As CIN is tightly correlated with drug resistance in cancer, we evaluated whether BUB1B OE could overcome sensitivity to BTZ or ADR in MM cells." (PMID 34620840, 2021). "BUB1B (BUB1 mitotic checkpoint serine/threonine kinase B) encodes a kinase involved in spindle checkpoint function and mitosis and plays an important role in the development of many types of cancer." (PMID 32528520, 2020).
cancer (continued). "Upregulation of BUB1B can prevent aneuploidy and cancer and prolong healthy lifetime." (PMID 33186389, 2020). "BUB1B has been reported as being important in two of these tumours, but germline variants have not been reported as being associated with these cancer types (OMIM ID: 602860)." (PMID 29641532, 2018). "In addition, the subtraction of gene expression of TCF21 and BUB1B can be a good predictor of OS in adult carcinomas, whereas the TCF21-NR5A1 can be a molecular predictor of malignancy in pediatric ACTs." (PMID 29520253, 2018). "Interestingly, recurrent mutations of genes previously reported to be mutated in cancer: ABL1, BUB1B, NCOR1 (each mutated in three tumours), and CARS, HSP90AB1, NCOA1 (each mutated in two tumours) were uniquely found in recurrent/metastatic NPCs (n=33)." (PMID 28098136, 2017). "Interestingly, though, higher-level BUB1B expression seems to be a much more frequent event in a wide variety of human cancers and has been described as a prognostic marker for tumor recurrence and disease progression." (PMID 26000094, 2015). "BUB1B is significantly overexpressed in a majority of human cancers." (PMID 26000094, 2015). "Given the critical role of BUB1B in mitotic checkpoint signaling and chromosome congression, impairment in BUB1B often results in aneuploidy and chromosomal instability, which can contribute to increased cancer incidence." (PMID 26000094, 2015). "However, whether BUB1B plays a role in cancer metastasis and the relevant mechanisms remains unknown." (PMID 41163302, 2025). "Notably, the different roles of BUB1B in various types of cancer may be attributed to tumor heterogeneity." (PMID 41163302, 2025). "Furthermore, it was observed that BUB1B was highly expressed in most cancer cell lines." (PMID 40076684, 2025). "Nevertheless, the role of BUB1B as a cancer-predisposing gene is not yet clarified." (PMID 39014450, 2024). "However, solid and mechanistic evidence establishing a link between specific BUB1B monoallelic variants and cancer predisposition are lacking." (PMID 39014450, 2024). "Notably, BUB1B showed a positive association with DNA and RNA for several different forms of cancer types but showed a negative correlation with RNA for THYM." (PMID 37055476, 2023). "BUB1B is highly expressed in a variety of cancers and may serve as a prognostic marker." (PMID 37055476, 2023). "Up to now, one of the best described molecular events that can be attributed to MVA1 pathogenesis is the failure of mitotic checkpoint and ciliary functions caused by BUB1B mutations, which are indeed associated with a more severe disease phenotype and increased cancer risks." (PMID 35804254, 2022). "Therefore, the molecular function of BUB1 and BUB1B genes in HD cancers should be further examined." (PMID 35757968, 2022). "Considering the important role of BUB1B in mitotic checkpoint signaling and chromosome assembly, BUB1B imbalance often leads to aneuploidy and chromosomal instability, which may lead to an increase in the incidence of cancer." (PMID 36577966, 2022). "However, the role of BUB1B in other types of cancer cells is still controversial." (PMID 30765611, 2019). "However, the true mechanism of BUB1B in cancers remains to be elucidated." (PMID 30100882, 2018). "Moreover, some studies have proven the role of BUB1B in cancers." (PMID 29246203, 2017). "The dissociation between BUB1B overexpression and cell proliferation in some human cancers, and the change of BUB1B protein localization during malignancy could imply that an alternative pathway other than, or in addition to, mitotic checkpoint signaling is involved in tumor progression." (PMID 26000094, 2015). "Our study found a positive correlation between BUB1B expression and MSI in seven cancer types (STAD, LUSC, COAD, UCEC, SARC, LIHC, ACC) and a negative correlation in DLBC." (PMID 40076684, 2025).
cancer (continued). "CCNB1, PLK1, CDK1, BUB1B, AURKA, and NDC80 are genes involved in various stages of the cell cycle process, which is crucial from a cancer perspective." (PMID 40287845, 2025). "BUB1B inhibitors have been developed to disrupt the SAC and induce mitotic arrest and apoptosis in cancer cells." (PMID 41439111, 2025). "To explore the pan-cancer role of BUB1B, we used in silico BubR1 molecular modeling, in vitro gene-editing, and ex vivo patients’ tumors and peripheral blood lymphocytes." (PMID 39014450, 2024). "Inhibiting the activity of BUB1B, TTK, and BUB3 can impede cancer cell proliferation, migration, and invasion." (PMID 38410481, 2024). "However, the expression and roles of BUB1 and BUB1B in pan-cancer and EC is unknown." (PMID 39048649, 2024). "The results showed that the protein expressions of BUB1 (P < 0.001), BUB1B (P = 0.025), CCNA2 (P < 0.001), and CDCA8 (P = 0.002) were significantly up-regulated in the cancer tissues." (PMID 37853361, 2023). "The relationship between BUB1B expression level and DSS, DFI, as well as PFI was also calculated in each cancer type." (PMID 37055476, 2023). "Cancer stage-wise expression analysis of the hub genes revealed that the expressions of TTK, BUB1B, and NUSAP1 increased while the expression of ZWINT decreased slightly with the stage-wise continued progression of OC." (PMID 37304238, 2023). "BUB1B (BUB1 mitotic checkpoint serine/threonine kinase B) has been reported to contribute to the initiation and development of several cancers." (PMID 35068350, 2022). "Further, graph centrality measures suggested the importance of upregulated genes such as BIRC5, UBE2C, BUB1B, KIF20A and PTH1R in cancer." (PMID 34728699, 2021). "For the six cancer types (BRCA, KIRC, LUAD, LUSC, PRAD, and THCA) containing >50 normal samples, BUB1B, KIF4A, and MELK were among the 30 with the most significantly upregulated local entropy of four cancer types." (PMID 34097054, 2021). "Meanwhile, CDK1, CCNA2, CCNB2, BUB1B and CDC20 were classified as cancer-related genes, and RRM2 was an FDA approved drug target." (PMID 33083112, 2020). "We found that the hub genes (BUB1B, CDC25C, CENPE, kinesin and CCNB1) make up an essential response across many cancer types." (PMID 31396397, 2019). "Besides the cell division-associated genes like CCNB2 and BUB1B, we also found genes such as TPX2, BIRC5, TOP2A, SPAG5 and HMGB1, were among the top 10 highly expressed genes in the cell subset, which were reported to be directly or indirectly associated with cancer invasion." (PMID 31888172, 2019). "BUB1B is a key component in the SAC protein family, which has been proven to be involved and upregulated in multiple human cancers." (PMID 30100882, 2018). "According to their data, the combined expression of BUB1B and PINK1 was the best predictor of OS among carcinomas." (PMID 29520253, 2018). "We have identified a number of protein kinase genes which are upregulated commonly in cancers and are involved in the cell cycle regulation such as PLK1, TTK, BUB1, BUB1B, and PKMYT1." (PMID 28427185, 2017). "Fourteen genes that are essential to prevent EDR in cancer cells also are essential to prevent aneuploidy in mice [AURKA, BUB1B, BUB3, KIF11, MAD2L1, TPX2, TTK, SGOL1." (PMID 27144335, 2016).
cancer (continued). "However, the mechanisms by which increased BUB1B expression mediates tumor progression are likely to be complex as BUB1B overexpression is not always associated with increased cell proliferation in human cancers and has been found in nondividing cells as well." (PMID 26000094, 2015). "The common signature at relapse also unveils several genes already described in the death-from-cancer signature including MKI67, KNTC2 (HEC1) and BUB1B." (PMID 20885975, 2010). "Additional genes with known relevance to human cancer identified by this SNCP model included glutathione peroxidase 2 (GPX2), the mitotic checkpoint protein kinase BUB1B, and the progestin-induced protein DD5." (PMID 18425214, 2007). "As a consequence, BUB1B-edited cells showed an increase in both PCS and lagging chromosomes, markers of CIN, which correlated with decreased sensitivity to Taxol-induced growth inhibition, as observed in other cancer models." (PMID 39014450, 2024). "This suggests that monitoring the levels of TTK, BUB1B, and BUB3 could potentially be useful in predicting the severity of carcinomas and guiding treatment decisions." (PMID 38987356, 2024). "BUB1B was shown to have a non-negligible role in pan-cancer, which is connected to immunology, cancer stemness, and genetic alterations in a variety of cancer types." (PMID 37055476, 2023). "Therefore, to the best of our knowledge, this study is the first to report the probable cancer-driving role of the hsa-mir-124-3p miRNA with respect to TTK, BUB1B, NUSAP1, and ZWINT hub genes in OC." (PMID 37304238, 2023). "APC (P), BRCA2 (P), BUB1B (LP), ENG (LP) and MSH6 (P) were identified in patients with cancer." (PMID 36896836, 2023). "Given the critical role of BUB1B in mitotic checkpoint signaling and chromosome congression, impairment in BUB1B and SAC often results in aneuploidy and chromosomal instability, which can contribute to an increase in cancer incidence." (PMID 33431813, 2021). "Furthermore, BRCA1 knockdown in human cancer cells downregulates transcription of multiple mitotic genes, including the BUB1, BUBR1/BUB1B, AURKA, ESPL1, and PTTG1 SAC genes." (PMID 32604778, 2020). "Indeed, both upregulation of BUB1B and CCNB1 were found to be a marker for unfavourable prognosis across several cancer types." (PMID 31396397, 2019). "In addition, among adult malignant tumors, the combined expression of TCF21 and BUB1B was a good predictor of OS." (PMID 29520253, 2018). "The difference between BUB1B and PTEN-induced putative kinase 1 (PINK1) expression has been described previously to be associated with survival in adult but not in pediatric carcinomas." (PMID 29520253, 2018). "Moreover, it is involved in tumorigenesis through the activation of PLK1, BUB1B and C-MYC, and repression of CDKN1B during cancer progression." (PMID 27270442, 2016). "As expected, BUB1B was expressed at high levels in the normal esophageal tissues of patients without cancer and underexpressed in patients with cancer." (PMID 18425214, 2007). "BUB1B and CDK1 may act in concert with HELLS, contributing to cancer malignancy and progression." (PMID 35774795, 2022). "Furthermore, CHEK1, BUB1B, and MCM2 could promote cancer cell proliferation, and which were enriched in cell cycle pathways in GSEA analysis for CCA." (PMID 33221765, 2020). "BUB1B is also a cellular target of synuclein-gamma (SNCG, also known as breast cancer specific gene 1), with which it may interact to inactivate the mitotic checkpoint, and contribute to resistance of beast cancer cells to microtubule inhibitors." (PMID 21785684, 2011).